ADCY3 (adenylate cyclase 3)
Diseases named in the same sentence as ADCY3 in open-access papers (continued):
Sharing a sentence is not in itself a finding about the gene and the disease.
tumor (10 papers, 2004 to 2025). "Tumoroids demonstrated upregulation of oncogene-associated genes (Ackr3, Adcy3, Fam222) and downregulation of tumor suppressor genes (Casz1, Frk, Homer2, Pdlim1)." (PMID 40772227, 2025). "For example, ADCY3 is a membrane-associated protein that is widely expressed in human tissues, and it exhibits tumor-promoting effects via the cAMP/PKA/CREB pathway." (PMID 34367229, 2021). "In vivo tumor growth was determined by subcutaneously injecting Adcy3‐ or Inpp4b‐silenced 4C11+ cells into mice flank region." (PMID 35075772, 2022). "We next determined how Adcy3 and Inpp4b in vivo tumor growth and in vivo metastatic potential using siRNA knockdown technology." (PMID 35075772, 2022). "Together, these results show for the first time the potential role of Adcy3 in in vivo tumor growth and the involvement of Inpp4b in tumor aggressiveness and metastasis formation." (PMID 35075772, 2022). "We identified adenylate cyclase type 3 (Adcy3) and inositol polyphosphate 4‐phosphatase type II (Inpp4b), which affect tumor growth and metastatic potential, respectively." (PMID 35075772, 2022). "ADCY3 knockdown reduced cell proliferation in vitro and suppressed tumor growth in a xenograft tumor model in vivo." (PMID 24113161, 2013). "Here we investigated the tumor-promoting effects of ADCY3 overexpression and confirmed a significant correlation between the upregulation of ADCY3 and Lauren's intestinal-type gastric cancers." (PMID 24113161, 2013). "In addition, Adcy3 overexpression has been shown to play a role in cell migration, proliferation, and tumor invasion." (PMID 33578738, 2021). "Results from a xenograft model also indicate that ADCY3 plays a crucial role in tumor growth." (PMID 24113161, 2013). "We used knockdown experiments to confirm the tumor-promoting effects of ADCY3 overexpression." (PMID 24113161, 2013). "Mice injected with Adcy3‐silenced 4C11+ cells (siAdcy3) developed smaller tumors in size and weight when compared to controls, suggesting that this gene may play an important role in tumor growth and development." (PMID 35075772, 2022). "Thus, ADCY3 overexpression may exert its tumor-promoting effects via the cAMP/PKA/CREB pathway." (PMID 24113161, 2013).
metabolic disorders (6 papers, 2018 to 2025). "In contrast, the loss-of-function mutation in ADCY3 leads to decreased lipolysis and increased lipid storage, which could predispose cells to lipid overload and related metabolic disorders." (PMID 39519366, 2024). "Moreover, mice with a gain-of-function mutation in Adcy3 presented increased Adcy3 activity and cAMP production and consequently the mutation protects mice from high fat diet-induced metabolic disorders." (PMID 29921800, 2018).
infection (5 papers, 2007 to 2024). The state of being infected such as from the introduction of a foreign agent such as serum, vaccine, antigenic substance or organism. "A number of pathways related to cardiac myopathy were also inhibited by inulin in both infection models, as a consequence of the suppression of many genes encoding voltage-dependent calcium channels (e.g., Cacng4) and cAMP formation (e.g., Adcy3)." (PMID 38179939, 2024). "strains showed an exclusive group in IC annotated as an adenylate cyclase 3 (cya3), which modulate the extent of epidermal infection during nodulation." (PMID 34557206, 2021).
ADCY3 also shares sentences with these, for which no sentence is quoted: diabetes (8 papers); dyslipidemia (5); ciliopathy (3); myopia (2); renal cystic disease (2); Adult onset (1); alcohol dependence (1); Arrhythmia (1); astrocytoma (1); behavioral disorders (1); brain injury (1); cognitive deficits (1); colon cancer (1); COVID-19 (1); dental caries (1); ependymoma (1); glioblastoma (1); Hyperinsulinemia (1); Hypertension (1); hyperuricemia (1); influenza (1); nephrogenic diabetes insipidus (1); neuroblastoma (1); pancreatic cancer (1); periodontitis (1); sarcopenia (1); type 1 diabetes mellitus (1); viral infection (1).